IL2RG (interleukin 2 receptor subunit gamma)
Description:
Common subunit for the receptors for a variety of interleukins. Probably in association with IL15RA, involved in the stimulation of neutrophil phagocytosis by IL15.
Synonyms: IL-2RG; CD132; CIDX; IMD4; P64; SCIDX; SCIDX1
Tractability: Small molecule: a structure with a bound ligand is known. Antibody: UniProt places it where antibodies can reach, with high confidence; its Gene Ontology location is reachable by antibodies, with high confidence; UniProt predicts a signal peptide or a membrane-spanning region; the Human Protein Atlas places it where antibodies can reach. PROTAC: ubiquitination databases record sites on it. Other modalities: a drug acting on it is in phase 2 or 3 trials.
Gene: Protein-coding gene on chromosome X (71,107,404 to 71,112,108, reverse strand). Ensembl gene ENSG00000147168.
Subcellular location: Cell membrane; Cell surface
Subcellular location (Human Protein Atlas): Plasma membrane; Nucleoplasm
Pathways (Reactome):
Immune System: Interleukin receptor SHC signaling; Interleukin-15 signaling; Interleukin-2 signaling; Interleukin-21 signaling; Interleukin-4 and Interleukin-13 signaling; Interleukin-7 signaling; Interleukin-9 signaling
Signal Transduction: RAF/MAP kinase cascade; STAT3 nuclear events downstream of ALK signaling
Gene Ontology:
Molecular function: coreceptor activity; interleukin-15 receptor activity; protein binding; cytokine binding; cytokine receptor activity; interleukin-2 binding; interleukin-2 receptor activity; interleukin-4 receptor activity; interleukin-7 receptor activity
Biological process: cell surface receptor signaling pathway via JAK-STAT; cellular homeostasis; interleukin-15-mediated signaling pathway; interleukin-2-mediated signaling pathway; interleukin-7-mediated signaling pathway; interleukin-9-mediated signaling pathway; positive regulation of phagocytosis; cytokine-mediated signaling pathway; immune response; immunoglobulin mediated immune response; interleukin-4-mediated signaling pathway; leukocyte homeostasis; lymphocyte differentiation; natural killer cell activation; negative regulation of apoptotic process; negative regulation of Fas signaling pathway; negative regulation of tyrosine phosphorylation of STAT protein; positive regulation of leukocyte differentiation; positive regulation of leukocyte proliferation; positive regulation of MAPK cascade; positive regulation of T cell differentiation; positive regulation of tyrosine phosphorylation of STAT protein; signal transduction
Cellular component: cell surface; interleukin-15 receptor complex; interleukin-2 receptor complex; interleukin-4 receptor complex; membrane; plasma membrane; cytosol; endosome; external side of plasma membrane; interleukin-7 receptor complex; receptor complex
Gene-disease validity (ClinGen):
ClinGen rates the evidence that IL2RG causes each of these diseases.
T-B+ severe combined immunodeficiency due to gamma chain deficiency (X-linked): Definitive. Severe combined immunodeficiency (SCID) due to gamma chain deficiency, also called SCID-X1, is a form of SCID characterized by severe and recurrent infections, associated with diarrhea and failure to thrive.
Homologues: Orthologues: chimpanzee IL2RG (99% identical), macaque IL2RG (97% identical), dog IL2RG (84% identical), pig IL2RG (82% identical), guinea pig IL2RG (76% identical), rat Cxhxorf65 (74% identical), mouse Il2rg (70% identical), zebrafish lifra (13% identical), zebrafish lifrb (12% identical), zebrafish ghrb (10% identical), zebrafish ghra (8% identical), zebrafish il11ra (8% identical), and 5 more. Paralogues in human: IL6R (20% identical), LIFR (14% identical), OSMR (13% identical), IL12RB2 (12% identical), IL6ST (12% identical), CSF3R (12% identical), IL11RA (12% identical), IL27RA (12% identical), IL31RA (11% identical), CNTFR (10% identical), IL23R (10% identical), PRLR (10% identical), and 11 more.
Diseases named in the same sentence as IL2RG in open-access papers:
IL2RG is named in the same sentence as 189 diseases in open-access papers, as found by Europe PMC text mining. Sharing a sentence is not in itself a finding about the gene and the disease. The quoted sentences say what the papers report.
Immunodeficiency (62 papers, 2010 to 2026). Failure of the immune system to protect the body adequately from infection, due to the absence or insufficiency of some component process or substance. "According to a literature review, although T cell and NK cell deletions coexist in most IL2RG variant severe combined immunodeficiency children, there are also a small number of cases with normal NK cell counts." (PMID 39450341, 2024). "In zebrafish, an ample level of immunodeficiency for tumor transplantation can be attained by disrupting prkdc to impair T and B lymphocyte development, and mutating il2rg to eliminate mature natural killer (NK) cells." (PMID 38443437, 2024). "Nonsense mutation W155X in IL2RG was found in P5 and P6, leading to X-linked severe combined immune deficiency (SCID)." (PMID 36180657, 2022). "IL2RG controls lymphocyte development, growth, differentiation, and survival and is associated with allergic and autoimmune diseases, cancer, and immune deficiency." (PMID 34124265, 2021). "The clinical presentation combined with dysgammaglobulinemia suspected an inherited immunity disorder, which has been proven by Next Generation Sequencing as a novel c.458T > C; p.Ile153Thr IL2RG missense-mutation." (PMID 35052377, 2021). "In this study, the well-established IL2rg gene disruption model of immune deficiency allowed us to study the contributions of T cells to the development of RIHD." (PMID 32316187, 2020). "Mashimo and colleagues generated interleukin-2 receptor gamma chain knockout (IL2RG−/−) rats in the F344/Stm background using zinc-finger nucleases and reported that IL2RG−/− rats display similar immune deficiencies as the mouse model." (PMID 32316187, 2020). "Sanger sequencing of the RT-PCR products of IL2RG showed that only mutant IL2RG was expressed in the A633-1 and A633-2 piglets, which caused spleen and thymus hypoplasia and immunodeficiency." (PMID 31253764, 2019). "All cloned RAG1, RAG2, and IL2RG mutated piglets were raised in the conventional housing environment and piglets with immunodeficiency presented health issues." (PMID 31253764, 2019). "Rag2 and IL2rg mutations cause immune system disorders associated with T-, B-, and NK cell function and some cytokine activities." (PMID 31134127, 2019). "Mutation of the IL2RG gene results in a form of severe combined immune deficiency (SCID-X1), which has been treated successfully with hematopoietic stem cell gene therapy." (PMID 30261899, 2018). "In a further case, we confirmed a previously identified IL2RG variant in a proband with immune deficiency." (PMID 30049826, 2018). "We report here on ZFN-induced gene targeting of the rat interleukin 2 receptor gamma (Il2rg) locus, where orthologous human and mouse mutations cause X-linked severe combined immune deficiency (X-SCID)." (PMID 20111598, 2010). "Over the last decade, the identification of hypomorphic variants in patients previously diagnosed with Common Variable Immunodeficiency (CVID) has led to the association of milder phenotypes with variants of the IL2RG gene that are usually related to severe combined immunodeficiency." (PMID 40170851, 2025). "Mutations in IL2RG disrupt cytokine signaling, leading to developmental arrest of T lymphocytes, which further causes B lymphocyte dysfunction, ultimately leading to humoral and cellular immune deficiencies, namely X-SCID." (PMID 39176082, 2024). "Thus, in the colorless and immunodeficient Xenopus tropicalis line of mitf/prkdc/il2rg triple-knockout, further exploration is needed to determine the contribution of the mitf knockout to the immune deficiency of this organism." (PMID 38443437, 2024). "The down-regulated gene IL2RG encodes an important signaling component of many interleukin receptors, and IL2RG deficiency can result in differential signaling defects while its mutation may cause immunodeficiency." (PMID 32849815, 2020).
Immunodeficiency (continued). "Mutations in 6 genes (IL12RB1, CYBB, IFNGR1, IL2RG, STAT1, and RAG1) account for 66% of BCG-associated immunodeficiency mutations." (PMID 41748971, 2026). "With regard to other clinical symptoms, granulomatous infiltrations and autoimmune complications have been described in combined immunodeficiencies associated to RAG and particularly, IL2RG hypomorphic variants." (PMID 40170851, 2025). "Pathogenic variants on the IL2RG gene are typically associated with X-linked SCID (T-B+NK- SCID), an immunodeficiency that profoundly affects both cellular and humoral immunity." (PMID 40170851, 2025). "Collectively, IFNG, IL2RG, FCGR3A, and ICAM1 associated with immune diseases were selected from the core genes through manual screening." (PMID 40844079, 2025). "The results showed that protein levels of INFG, IL2RG, and FCGR3A associated with immune diseases were evidently upregulated (p < 0.001), while CAM1 protein levels were significantly downregulated as the differentiation time prolonged (p < 0.01)." (PMID 40844079, 2025). "Through bioinformatics analysis, the core genes INFG, IL2RG, FCGR3A, and ICAM1 associated with immune diseases were screened and their expressions were also measured at the protein level." (PMID 40844079, 2025). "Knockdown of IL2RG is a common method to generate mouse models with impaired immune function, allowing the study of human immunodeficiency diseases." (PMID 40096084, 2025). "IL2rg and JAK3 mutations were introduced into NOD‐SCID mice in order to further enhance immune deficiency in the mice." (PMID 38591343, 2024). "These mice were generated by mating NRG mice possessing a genetic defect (Rag2/Il2rg) conferring immunodeficiency, and Alb‐rtTA/TRE‐uPA mice capable of producing endogenous liver damage in the presence of doxycycline." (PMID 37864397, 2024). "Most IL2RG pathogenic mutations lead to severe T-cell defects, further causing typical SCID characterized by T-B+NK-immunodeficiency." (PMID 39176082, 2024). "To assess the immunodeficiency of this strain, we performed allotransplantation of wild-type skin to both mitf−/− and mitf−/−/prkdc−/−/il2rg−/−Xenopus tropicalis, and observed immune rejection responses and T cell infiltration." (PMID 38443437, 2024). "Rats with knockout of the Il2rg and Rag2 genes exhibit significant immunodeficiency, characterized by a reduction in WBC counts and hypoplasia of the spleen and thymus, which are hallmark features of a SCID phenotype." (PMID 39731164, 2024). "The most frequent main genetic causes of cellular and humoral immunodeficiencies in children infected with SARS-CoV-2 were DOCK8 deficiency (n = 6), IL2RG (n = 5), RelB deficiency (n = 3), JAK3 deficiency (n = 3), and IL7Ra deficiency (n = 3)." (PMID 37559153, 2023). "For example, lymphoedema is also seen in some cases of Interleukin 2 Receptor Subunit Gamma (IL2RG)/Janus Kinase 3 (JAK3) severe combined immunodeficiency, in which a primary lymphopoietic disorder appears to modify lymphangiogenesis." (PMID 34916230, 2023). "Since IL2RG plays a crucial role in the development, differentiation, and function of T, B, and NK cells, defects in this gene lead to severe immunodeficiency." (PMID 37661226, 2023). "CRISPR/Cas9 system and somatic cell cloning technology were used to generate two pig models with FAH deficiency and exhibiting severe immunodeficiency (FAH/RAG1 and FAH/RAG1/IL2RG deficiency)." (PMID 35255981, 2022). "The immunodeficiency phenotype was preliminarily confirmed by the presence of severe thymic hypoplasia in Il2rg-single knockout (sKO) and Il2rg/Rag2-double knockout (dKO) rats." (PMID 35960733, 2022). "The immunodeficiency phenotypes exhibited by Il2rg-sKO and Il2rg/Rag2-dKO rats were comparable to the phenotypes of our previously developed immunodeficient rat models." (PMID 35960733, 2022). "These severe immunodeficiency features highlight the importance of IL2RG in the development of adaptative immunity and innate immunity." (PMID 35954238, 2022).
Immunodeficiency (continued). "The constructed FAH/RAG1/IL2RG triple-knockout pig models were characterized by chronic liver injury and severe immunodeficiency." (PMID 35255981, 2022). "Immunodeficiency was preliminarily confirmed by the presence of severe thymic hypoplasia in Il2rg-sKO and Il2rg/Rag2-dKO rats, whereas thymic morphology was similar between double heterozygous mutant female rats and WT female rats." (PMID 35960733, 2022). "A higher tolerance to toxicity is offered by mice that combine Il2rg and recombinase-activating gene (Rag)-1 or -2 knockouts (e.g., BALB Rag−/−;Il2rg−/− or NOD Rag−/−;Il2rg−/−), which generally have the same level of immune deficiency as NSG mice." (PMID 33671173, 2021). "This led us to study the functional role of T cells in promoting radiation-induced cardiotoxicity using a genetic model of immunodeficiency, i.e., the IL2RG−/− SS rat which lacks functional T and B cells and exhibits decreased NK activity." (PMID 32316187, 2020). "IL2RG knockout mice showed immunodeficiency and high tumorigenic engraftment efficiency of human cancer cells and tissues." (PMID 33232279, 2020). "Mice with IL2rg gene disruption have x-linked severe combined immunodeficiency (X-SCID), with the immunodeficiency characterized by a profound loss of T cells, B cells, and NK cells, and IL2RG−/− rats display similar immune cell deficiencies." (PMID 32316187, 2020). "We chose C57BL/6 wild-type (WT) and six well-characterized immunodeficient mouse strains, namely nude, scid, NOD-scid, B6.129S4-IL2Rg−/− (IL2Rg−/−), Rag2−/−, and NOD-scid-IL2Rg−/− mice, to assess immunodeficiency." (PMID 26022250, 2015). "The MENA registry also reported high mortality in non-syndromic combined immunodeficiencies (51.7%) and syndromic CID (22.5%), particularly in patients with RFXANK, RAG1, and IL2RG mutations, where the most common causes of death were infection and respiratory failure." (PMID 40806973, 2025). "The IL2RG and RAG1-deficient monkeys described in this study hold value not only for oncology research but also represent a significant step forward in utilizing monkeys as models for severe immunodeficiency diseases in humans and regenerative medicine." (PMID 37661226, 2023). "This high prevalence suggests that the Il2rg knockout may be an appropriate model for immunodeficiency." (PMID 35960733, 2022). "As the most severe immunodeficiency, severe combined immunodeficiency (SCID) is caused by a mutation in the gene encoding the interleukin 2 receptor gamma (IL2RG), which results in the developmental arrest of T cell production and additional primary or secondary defects in B cells." (PMID 32296011, 2020). "Pigs lacking functional IL2RG show symptoms of immune deficiency, including thymic atrophy, decreased or absent T lymphocytes and natural killer (NK) cells, and attenuation of B cell function." (PMID 31754342, 2019). "Thus, Rag2/IL2rg-/- knockout mice possessed features of severe combined immunodeficiency (SCID), which is an ideal model for human xenograft." (PMID 31134127, 2019). "X-linked severe combined immunodeficiency (X-SCID) is an immune disorder caused by mutations in the IL2RG gene and characterised by the absence of T and NK cells in patients." (PMID 28963568, 2017). "Disruption of IL2RG in male pigs resulted in immunodeficiency presented in X-linked SCID patients; these pigs lacked T and NK cells." (PMID 27809915, 2016). "This statement suggests that the activation of receptor complex {IL7R, IL2RG} may activate {JAK1, JAK3} to cause immunodeficiency disease." (PMID 27819359, 2016). "Alternatively, the F0 generation piglet, c12, which was a chimera for IL2RG gene mutation, could survive in conventional housing conditions without symptoms of immunodeficiency and transmit the IL2RG gene mutations to offspring." (PMID 31754342, 2019). "Recently, Severe Combined Immunodeficiency (SCID) rats were generated using CRISPR/Cas9 system, targeting Il2rg and Rag2 in National BioResource Project in Japan." (PMID 39731164, 2024).
Immunodeficiency (continued). "In summary, we have successfully generated IL2RG and RAG1 mutant monkeys with severe combined immunodeficiency using the CBE4max base editing system." (PMID 37661226, 2023). "On the whole, the reported percentages of successful engraftment of solid human tumors are roughly proportional to the degree of immunodeficiency (NSG and Rag−/−;Il2rg−/− > NOD/SCID > SCID > nude)." (PMID 33671173, 2021). "We successfully generated TYR-KO, IL2RG-KO, and RAG1-KO Tibet minipigs, which are phenotypically characterized by albinism and/or immunodeficiency." (PMID 31754342, 2019). "This study successfully achieved the generation of an immunodeficiency model in non-human primates by utilizing the CBE4max system to introduce specific single-nucleotide substitutions in the IL2RG and RAG1 genes." (PMID 37661226, 2023). "IL2RG-KO and RAG1-KO Tibet minipigs exhibited an apparent immunodeficiency phenotype." (PMID 31754342, 2019). "NSG mice (non-obese diabetic-severe combined immunodeficiency/y-chain; NOD-Prkds IL2rg) combine a severe immune deficiency mutation [SCID] and IL-2 receptor y-chain deficiency." (PMID 28800593, 2017). "We transplanted the outgrown cells of starting matched doses (1 × 105) of UCB-derived GE-HSPCs co-cultured with MSCs or standard GE-HSPCs, as control, into sublethally irradiated immunodeficient non-obese diabetic (NOD)-severe combined immunodeficiency (SCID)-IL2Rg−/− (NSG) mice." (PMID 35982622, 2023). "Taken together, our results suggest that a small deletion of 2 bp in the IL2Rg gene of NOD/SCID mice by CRISPR/Cas9 system is sufficient to induce a severe immunodeficiency not available in nude and NOD/SCID mice, that could be used for cell engraftment of tumors." (PMID 32817844, 2020). "The full functional characterization of bone and striated muscle microcirculatory parameters in non-obese diabetic-severe combined immunodeficiency/y-chain; NOD-Prkds IL2rg (NSG) mice has not yet been reported." (PMID 28800593, 2017).